GPR65 (G protein-coupled receptor 65)
Diseases named in the same sentence as GPR65 in open-access papers (continued):
Sharing a sentence is not in itself a finding about the gene and the disease.
tumor (continued). "For instance, GPR65 overexpression in Lewis lung carcinoma (LLC) cells increased primary tumor growth in a murine model and promoted resistance to acidosis-mediated cell death through PKA/ERK signaling." (PMID 39336742, 2024). "GPR65 is a member of the proton-sensing G protein-coupled receptor family, which is closely related to tumor microenvironment (TME)." (PMID 38218960, 2024). "TCR-T cells co-cultured with A375 cells showed efficient tumour cell killing, which was further improved in presence of the GPR65 inhibitors, SD2758 and SD2571 being the most active compounds." (PMID 39483470, 2024). "A recent study also showed that GPR65 on TAMs sensed lactate in the tumor microenvironment in order to induce the secretion of HMGB1 through the cAMP/PKA/CREB pathway to exacerbate glioma progression." (PMID 39336742, 2024). "The differentially expressed GPR65, DPP4, and CXCR6 are involved in the anti-cancer efficacy of PD-1 blockade by affecting the recruitment of tumor-associated macrophages or CD8 + T cells." (PMID 38698468, 2024). "Acidity in the tumor microenvironment upregulated the expression of the immune checkpoint molecule PD-L1 through the proton-sensing GPCRs, including GPR65." (PMID 39336742, 2024). "High expression of GPR65 predicted the enhancement of immune response, anti-inflammatory and anti-tumor ability." (PMID 38218960, 2024). "To assess the impact of inhibiting GPR65 or HMGB1 on tumor progression in an in vivo context, we subcutaneously injected U87 cells, with or without tumor-associated macrophages (TAMs), into nude mice to establish subcutaneous xenograft tumors." (PMID 38576043, 2024). "Together, these data collectively demonstrated that the tumor-promoting effects of TAMs were counteracted by GPR65-silence on TAMs." (PMID 38576043, 2024). "It has been proposed that GPR65 functions as a potential immune checkpoint in the tumor microenvironment." (PMID 39336742, 2024). "Restoring GPR65 gene expression in U937 cells inhibited cell proliferation in vitro and reduced tumor growth and metastasis in vivo." (PMID 39336742, 2024). "Conversely, GPR65 knockdown (group III) significantly attenuated tumor growth compared to the shNC-TAM group (group II)." (PMID 38576043, 2024). "GPR65 is a pH-sensing G protein-coupled receptor that acts as a key innate immune checkpoint in the human tumor microenvironment, inhibiting the release of inflammatory factors and inducing significant upregulation of tissue repair genes." (PMID 38218960, 2024). "In summary, these results collectively underscore that among the receptors implicated in lactate signaling, GPR65 is prominently expressed in GBM, with its primary localization on tumor-associated macrophages, especially M2-TAMs." (PMID 38576043, 2024). "Collectively, these findings demonstrated the pivotal role of GPR65 in cytoskeletal reorganization that facilitates tumor cell migration." (PMID 38218960, 2024). "We collected from the TISCH2 resource a total of 72 public TME scRNAseq datasets spanning 30 indications to assess GPR65 mRNA expression levels in tumour-infiltrating immune cells." (PMID 39483470, 2024). "As previously reported, GPR65 gene expression was detected in almost all tumour-infiltrating monocytes/macrophages." (PMID 39483470, 2024). "Summarize all, the tumor-promoting effects of lactate stimulated TAMs were mediated by GPR65 through the secretion of HMGB1." (PMID 38576043, 2024). "Overexpression of GPR65 in tumor cells can promote cell survival and growth in an acidic environment and induce tumor development in mice." (PMID 37723567, 2023). "GPR65 promotes their survival and growth in acidic conditions, which would mean an advantage in the tumor environment." (PMID 33113952, 2020). "Lactate, the main end product of glycolysis in cancer cells, is released in the tumor microenvironment where it is able to interact with specific receptors, such as the G-protein coupled receptor-65 (GPR65)." (PMID 31467175, 2019).
tumor (continued). "GBM was found to be the tumor type with the highest expression levels of the lactate receptor GPR65 at the mRNA level." (PMID 31467175, 2019). "Highly sensitive and specific antibodies to GPR65 are needed for future studies to be carried out, with the long-range goal of employing GPR65 as either a novel tumor marker or novel therapeutic target." (PMID 25984552, 2014). "Although we cannot discern the distinct impact of heterogeneous macrophage subsets, their numbers, and polarization on CAR T-cell therapy resistance, the complete reversal of GPR65 KO tumor resistance upon macrophage depletion confirms their critical role in CAR T-cell therapy resistance." (PMID 39998425, 2025). "On the other hand, overexpression of GPR65 enhanced these abilities of tumor cells." (PMID 40519919, 2025). "Tumors from GPR65 overexpressing tumor cells were smaller and lighter." (PMID 40519919, 2025). "Another study showed that overexpression of GPR65 in Lewis lung cancer cells stimulated tumor cell growth and may promote resistance to acidosis-mediated cell death in vitro via protein kinase A (PKA) and ERK-related pathways." (PMID 40519919, 2025). "This suggested that alterations in the TME may have mediated CAR T resistance to GPR65 KO tumors and led to the hypothesis that tumor cells rewired tumor–TME interactions, leading to the local ineffectiveness of CAR T cells." (PMID 39998425, 2025). "Collectively, these data suggest that GPR65 is an oncogene in vivo that inhibits tumor growth." (PMID 40519919, 2025). "Furthermore, given the high expression of CA9 in RCC tumours secondary to VHL loss and constitutive HIF activation, GPR65 represents a rational therapeutic target in this disease context." (PMID 41375084, 2025). "As expected, CAR T cells were unable to control GPR65 KO tumor cells." (PMID 39998425, 2025). "We next assessed GPR65 KO tumor response to anti-CD19 CAR T-cell therapy." (PMID 39998425, 2025). "GPR65-mediated suppression of tumor VEGFA production plays a prominent role." (PMID 39998425, 2025). "Although described as an oncogene in solid tumors and a tumor suppressor in hematologic malignancies, GPR65 has not previously been associated with susceptibility to immunotherapy." (PMID 39998425, 2025). "This indicates that GPR65 is involved in the tumor immune regulatory response of OS." (PMID 38218960, 2024). "GPR65 can also modulate the tumor immune microenvironment (TIME)." (PMID 39336742, 2024). "Notably, we show that GPR65 agonism, like other G-α coupled GPCRs, substantially altered human T-cell activation and functions in response to tumour cells." (PMID 39483470, 2024). "Moreover, T-cells co-cultured with target tumour cells in standard cell culture medium showed improved effector functions in presence of both GPR65 antagonists, implying that GPR65 likely restrains T-cell functions in non-acidic conditions." (PMID 39483470, 2024). "As our tumour-antigen killing system showed a GPR65 antagonist-driven increased T cell cytotoxicity, we assessed any correlation with T cell functional phenotypes by assessing TCR-driven T cell activation markers, proliferation and intracellular IFN-γ production." (PMID 39483470, 2024). "Considering that extra-cellular milieu acidification consequent to a highly glycolytic cancer cell metabolic state is a common feature of solid tumours, we were interested in the potential immune suppressive role of GPR65 in the context of T-cell anti-tumour immunity." (PMID 39483470, 2024). "Or is it because GPR65 is strongly expressed in lymphoid tissue (tumor suppressor factor), its activation may represent a potential anti-tumor biomarker?" (PMID 38218960, 2024). "On the other hand, the elevated levels of GPR65 expressed across several cancer types combined with the acidosis present in solid tumors may point to a role of this receptor in the tumor microenvironment." (PMID 39028811, 2024).
tumor (continued). "Our results broaden the scope of GPR65 as an IO target by suggesting that its inhibition may enhance T-cell anti-tumour activity and provide useful pharmacological tools to further investigate the therapeutic potential of GPR65 inhibition." (PMID 39483470, 2024). "Further fractioning of the patient population based on tumour immune contexture hinted that the positive correlation between survival and the GPR65 SNP may be more pronounced in the context of an inflammatory TME." (PMID 39483470, 2024). "Moreover, we provide evidence that antagonizing GPR65 with small molecule inhibitors improves the ability of T-cells to inhibit the growth of tumour cells in vitro and augments cytokine secretion by T-cells." (PMID 39483470, 2024). "Finally, the inhibition of GPR65 or the blockage of HMGB1 effectively alleviated the tumor-promoting effects of lactate-stimulated TAMs." (PMID 38576043, 2024). "Furthermore, we validated novel GPR65 small compound antagonists that promoted the anti-tumour activity of T-cells and increased their cytokine secretion." (PMID 39483470, 2024). "Total T-cells engineered to express transgenic TCRs from lentiviral vectors specific for the tumour associated epitopes HLA-A2/NY-ESO1157-165 or HLA-A2/MAGE-A4230-239, both expressed by the A375 target cell line, were exposed to GPR65 agonists in killing and cytokine secretion assays." (PMID 39483470, 2024). "However, there are studies indicating that GPR65 exhibits tumor suppressor functions in certain tumors." (PMID 37723567, 2023). "Additionally, GPR65 has been found to be markedly downregulated in hematological malignancies, leading to reduced tumor cell proliferation specifically under conditions of pH 7.4 and severe acidosis (pH 6.4)." (PMID 37723567, 2023). "Thus, different data suggest that the presence of GPR65 in tumor cells has the potential to affect the carcinogenic process, which seems logical as this receptor reacts to the extracellular acidosis commonly encountered in tumors." (PMID 33113952, 2020). "In order to address the existence of metabolic regulation of the tumor immune microenvironment, we analyzed the expression levels of the lactate receptor GPR65, a cell surface receptor recently reported to dampen local tumor immunity by interfering with the function of TAM." (PMID 31467175, 2019). "Despite NUSAP1, GPR65 proved to promote tumor growth in cancer." (PMID 30356407, 2018). "In addition, the accumulation of oleic acid within the tumor microenvironment could promote tumor growth by activating macrophage signaling through the acid-sensing receptor GPR65." (PMID 41614948, 2026). "In RCC specifically, ex vivo studies using tumour fragments from RCC patients have demonstrated that GPR65 inhibition modulates cytokine profiles within the TME, suggesting that the acid-sensing GPR65 pathway may contribute to the immunosuppressive landscape characteristic of this malignancy." (PMID 41375084, 2025). "It was reported that GPR65 may be involved in regulating tumor progression through TME." (PMID 40519919, 2025). "In various cancer types, GPR65 inhibition may inadvertently promote pro-tumour phenotypes—either by driving compensatory metabolic reprogramming or by altering macrophage polarisation in a way that supports tumour growth under specific conditions." (PMID 41375084, 2025). "Importantly, recent studies have found that GPR65 could be used as a key cancer immune checkpoint inhibitor in human tumor microenvironment, which could inhibit the release of inflammatory factors and induced significant up-regulation of tissue repair genes." (PMID 38218960, 2024). "However, GPR65 may have both protective and detrimental roles, for example, it is downregulated in hematological malignancies and functions as a tumor suppressor to promote apoptosis of murine lymphoma cells." (PMID 38001521, 2023).
tumor (continued). "With regard to its presence in tumor tissues, its overexpression has been detected in a proportion of kidney, ovarian, colon and breast tumors and in metastatic melanomas while, in contrast, a reduced expression of GPR65 has been observed in multiple hematological malignancies." (PMID 33113952, 2020). "In macrophages, lactate activates GPR65, promotes downstream cAMP/PKA/CREB activation, facilitates HMGB1 secretion and promotes tumor cell proliferation." (PMID 40165895, 2025). "GPR65 KO or m.CR tumors [red fluorescent protein–positive (RFP+)] and host immune cells (CD45.2+ Thy1.1− RFP−) were isolated from the spleen of tumor-bearing mice prior to CAR T-cell treatment (day 7) and 4 days after treatment (day 11) and analyzed." (PMID 39998425, 2025). "GPR65, also known as TDAG8, is a proton-sensitive GPCR that senses the acidic TME and transduces lactate- and acidosis-derived signals to regulate tumor and immune cell function." (PMID 41152975, 2025). "To further investigate the role of GPR65 in tumor responses to CAR T-cell therapy, we knocked out Gpr65 in the m.CR hCD19+ B-ALL cell line." (PMID 39998425, 2025). "In the context of the immune microenvironment, GPR65 signalling has been demonstrated to skew macrophages and other immune cells toward immunosuppressive phenotypes, contributing to a TME that supports tumour progression." (PMID 41375084, 2025). "Unbiased cell–cell communication analyses of tumor cells with host macrophages and monocytes pinpointed VEGFA as a major communication hub specifically upregulated in GPR65 KO tumors." (PMID 39998425, 2025). "Pathios has developed PTT-3213, a small molecule inhibitor of GPR65 that significantly increases CD8 + T cells and natural killer T (NKT) cells in the tumor microenvironment." (PMID 38218960, 2024). "In the same way, in almost all datasets, tumour-infiltrating CD8+ T-cells (CD8T) and exhausted CD8+ T-cells (exCD8T) expressed GPR65 gene." (PMID 39483470, 2024). "Two compounds described as GPR65 allosteric activators, BTB09089, a well-characterized and widely used GPR65 agonist, and ZINC13684400, were used in T-cell/tumour cell co-culture assays." (PMID 39483470, 2024). "Further RNA-seq results showed that high expression of GPR65 in U2OS cells can induce changes in immune system, metabolism, and signaling processes, and exert tumor inhibition through MAPK and PI3K/AKT signaling pathways." (PMID 38218960, 2024). "Based on standard TISCH cell type annotations, it appeared that tumour-infiltrating CD8+ T-cells expressed high GPR65 mRNA levels comparable to monocytes and macrophages, known to express functional amounts of GPR65 protein." (PMID 39483470, 2024). "In parallel, GPR65 silencing in human non-small cell lung cancer cells (NCI-H460), which constitutively express high levels of this receptor, significantly reduced tumor development in nude mice." (PMID 33113952, 2020). "To better understand the involvement of TDAG8 in various tumor types, we performed additional bioinformatic analyses of the Oncomine database to evaluate TDAG8 (GPR65) expression in cancerous and normal tissues." (PMID 29017562, 2017). "Low GPR65 activity is associated with resistance to anti-CD19 CAR T-cell therapy in both patients and an immunologically intact mouse model independent of tumor CD19 expression." (PMID 39998425, 2025). "Therefore, the inhibition of GPR65 in RCC offers the potential to concurrently disrupt both immune suppression and angiogenic pathways critical to tumour progression." (PMID 41375084, 2025). "Functional studies demonstrate that GPR65 is often overexpressed in solid tumours—including RCC—and that its activation enhances tumour cell survival under acidic conditions by engaging the cAMP-PKA and ERK signalling pathways—supporting continued proliferation even in the hostile TME." (PMID 41375084, 2025).
tumor (continued). "Similarly, CAR T cells from GPR65 KO tumors showed elevated expression of activation markers CD25 and CD69, consistent with the increased tumor burden and antigen exposure." (PMID 39998425, 2025). "In other words, GPR65 was mainly expressed on CD8 + T cells, CD4 + T cells, and tumor associated macrophages, but not on 8-cluster cells (osteoblasts or OS cells)." (PMID 38218960, 2024). "Nevertheless, our results point to substantial GPR65 expression in tumour CD8+ T-cells relative to other cell types and, by extension, reinforce the notion that GPR65 is expressed at functionally relevant levels in CD8+ T-cells, including the dysfunctional/exhausted subsets." (PMID 39483470, 2024). "These antagonists improved tumour antigen-specific killing by T-cells without showing direct cytotoxic effects on tumour cells, strongly suggesting that blocking GPR65 signaling enhanced T-cell killing in response to antigen." (PMID 39483470, 2024). "Recent reports have suggested that GPR65, a Gαs-coupled proton-sensing GPCR broadly expressed in the immune system, may act as an immune suppressant detrimental to anti-tumour immunity." (PMID 39483470, 2024). "Moreover, LGG tumors with CD302 or FABP5 overexpression highly expressed some oncogenes, including GPR65, PIK3CG, CHI3L1, and RAB36, which were reported to promote tumor growth and metastasis." (PMID 32775301, 2020). "Reduction of CX3CR1 expression leads to reduction in GPR65 and FFAR4 expression, which may affect tumor cell’s ability to uptake FAs, partially explaining reduced omental metastasis." (PMID 29712888, 2018). "However, a notable in vitro study validated a series of four novel GPR65 antagonists (SD2571, SD2593, SD2594, and SD2758) that were able enhance anti-tumour T-cell function and cytokine production in an acidic co-culture of immune cells and tumour cells." (PMID 41375084, 2025). "Indeed, the administration of CAR T cells and anti-VEGFA antibody significantly prolonged survival and reduced GPR65 KO tumor burden compared with mice receiving isotype control (no anti-VEGFA)." (PMID 39998425, 2025). "GPR65 blockade may not uniformly remodel immune landscapes across all tumour regions and could inadvertently support cancer stem cell niches or create selection pressures that confer survival advantages to more aggressive cancer cells." (PMID 41375084, 2025). "We interrogated two datasets reporting single cell trancriptomics with cells isolated from tumour and non-tumour tissues to assess whether GPR65 expression was different in T-cells found infiltrating healthy, tumoural or allergic tissues." (PMID 39483470, 2024). "To validate whether GPR65 on TAMs indeed functions as the critical sensor for lactate signaling in the TME to drive tumor progression, we transfected TAMs with either shNC (negative control shRNA) or shGPR65 (GPR65-silencing shRNA)." (PMID 38576043, 2024). "Therefore, our study suggests that GPR65 as a new immune checkpoint for immune checkpoint inhibitor anti-tumor therapy (ICI-therapy) is controversial, and at least not applicable to some malignant tumors, including OS." (PMID 38218960, 2024). "In the intricate landscape of the tumor microenvironment, the signal transduction triggered by lactate stimulation mainly relays on the lactate receptor HCAR1 (GPR81), and proton-sensing G-protein coupled receptors (GPRs), including GPR4, TDAG8 (GPR65), OGR1 (GPR68), and G2A (GPR132)." (PMID 38576043, 2024). "Furthermore, GPR65, identified as a lactate sensor in TAMs, detects lactate in the TME and initiates the downstream cAMP/PKA/CREB signaling pathway, promoting the release of high-mobility group box 1 (HMGB1) from TAMs and thereby accelerating tumor progression." (PMID 40165895, 2025). "Additionally, GPR65 inhibition was shown to skew the differentiation of CD4+ T-cells towards a Th1 profile at the expense of Th17 polarization, which could be beneficial in the context of most anti-tumour immune responses." (PMID 39483470, 2024).